CD4 (CD4 molecule)
Diseases named in the same sentence as CD4 in open-access papers (continued):
Sharing a sentence is not in itself a finding about the gene and the disease.
viral infection (continued). "Likewise, it is plausible that intercellular contacts between two resting CD4+CD25− cells could induce LFA1 conformational changes so as to transfer HIV between these cells, with the caveat that a productive viral infection may occur in the resting CD4+CD25− cells." (PMID 39810915, 2024). "Researches have demonstrated that the absence of mature B cells does not influence the development of virus-specific memory CD4+ T cells, which might play a role in providing resistance to viral infections in mice even when B cells and CD8+ T cells are missing." (PMID 39203969, 2024). "While CD4 T cell counts were similar and clinical co-morbidities such as active infection and AIDS defining illnesses were excluded, PWH participants selected for study may have had occult viral infections such as maternal CMV, that could influence the bioprofiles in the HEU infants." (PMID 39328414, 2024). "In cART, HIV is often combined with other types of viral infections due to low immunity, and studies have found that hepatitis B virus (HBV), hepatitis C virus (HCV), cytomegalovirus (CMV), Epstein–Barr virus (EBV), and other viruses may affect CD4+ T cell recovery and immune reconstitution." (PMID 37608956, 2023). "Although there were higher rates of detectable VL and failure to suppress viral infection among our PHIV patients, this group presented neither an increased risk of MTCT nor a higher prevalence of immunodeficiency signs, such as opportunistic infections and CD4+ cell count <200 mm." (PMID 36870111, 2023). "Helper T cells recognizing spike protein antigens correlated more strongly with the overall antibody levels to the same protein but not other proteins, suggesting that antigen-specific CD4+ T cell help may be required for robust development of antibodies during viral infections." (PMID 35439174, 2022). "Since exhausted T cells are heterogeneous, the precise features of exhaustion in CD4+ and CD8+ T cells are not comprehensively defined, “T-cell exhaustion” is still a broad term for a state which the effector T cells are dysfunction caused by chronic viral infection." (PMID 35432304, 2022). "In addition, we obtained 4 target pathways for CD19+ B cells and 15 target pathways for CD4+ T cells in Fingolimod for MS, 7 target pathways for pDCs and 6 target pathways for PBMC in IFN-β for MS, most of which belong to the immune system and viral infectious disease pathways." (PMID 36341423, 2022). "In addition, IAV-specific CD4+ T cells are key for the generation of virus-specific antibodies by B cells and the establishment of immunologic memory; additional functions are played by Foxp3+CD25+ regulatory CD4+ T cells (Tregs), Th17, and T follicular helper (TFH) cells during virus infection." (PMID 33746961, 2021). "However, these approaches showed a high variability in the expansion of the different γδ-T cell subpopulations (CD4, CD8, CD4–/CD8–, Vδ1, Vδ2, and Vδ1–/Vδ2–) and feasibility of gene-modification in order to improve persistence and efficacy against a broad range of tumours and viral infections." (PMID 31824502, 2019). "Interestingly, we observed an increase in the frequency of either CD4+ or CD8+ T cells producing TNF-α after immunization with the pE1D2 and challenge with DENV2, while lymphocytes from pcTPANS1-vaccinated animals maintained ordinary TNF-α production after virus infection." (PMID 31333657, 2019). "Indeed, during viral infections, allo-HLA-DP directed CD4 T-cells can induce GVHD, suggesting that also CD4 T-cells directed against broadly expressed HLA class II restricted MiHA may cause GVHD when HLA class II expression is upregulated on non-hematopoietic cells." (PMID 30619360, 2018). "The observations that the expression of HK2 appears non-essential for CD4 T cell responses against virus infections is of interest since it suggests that targeting HK2 for cancer therapy may not have untoward effects on CD4 T cell mediated immune response against virus infections." (PMID 29352298, 2018).
viral infection (continued). "The no fever group individuals had a reduced proportion of CD4+ T cells (p < 0.05, n = 10), whereas the group expressing behavioral fever had a significantly increased, twice, the proportion of CD4+ T cells in contrast to the no fever group during the viral infection (p < 0.05, n = 10)." (PMID 29915591, 2018). "Viral infection (presence or absence of provirus) and transcriptional status (presence or absence of viral gag RNA) was determined by real-time PCR in both unfractionated and individually enriched leukocyte subsets (CD4+, CD8+, and CD21+) from peripheral blood, MLN, and spleen." (PMID 28384338, 2017). "Since we believe that LILRA3 can be helpful in a virus infection due to its ability to induce proliferation in cytotoxic cell subsets, we hypothesize that expression of LILRA3 could indicate better disease status of the patients, i.e. lower viral load, higher CD4 and CD8 T-cell and NK-cell counts." (PMID 26969150, 2016). "However a potential cytotoxic role within this population has come to be discovered by the particular existence of an unusual small subset comprised by CD4+ T cells that do express NKG2D, which could represent a particular cytotoxic population involved in viral infections and chronic diseases." (PMID 26486970, 2015). "Thus, noncytotoxic control of viral replication by CD4+ T cells could be a more general mechanism for resolving numerous viral infections regardless of CD8+ T-cell activity." (PMID 26719800, 2015). "In addition, flow cytometry analysis also showed an increment in the populations of NK cells (CD45+ CD3 low, NK1.1+) and CD4+ lymphocytes (CD45+ CD4+) at the tumor site after viral injections in the tumor (p<0.05), indicating both innate and adaptive immunity were induced by the viral infection." (PMID 24827739, 2014). "Thus, a shared mechanism based primarily on preserving CD4+ TSCM and TCM cells from virus infection may underlie the lack of disease progression in both VNPs and SIVsmm-infected SMs." (PMID 25167059, 2014). "Coincidental with the lack of HCMV-specific CD4+ and CD8+ T cell response was the consistent positivity of viral markers in blood prompting antiviral treatment, while recovery of HCMV-specific CD4+ and CD8+ T-cell reponses was associated with spontaneous resolution of viral infection." (PMID 18798988, 2008). "Similarly, HIV-1 transgenic rats, despite the absence of characteristic viral disease progression, have an absolute reduction in CD4+, a reduced number of IFN-gamma-producing CD8+ T cells, and an increased susceptibility of T cells to activation-induced apoptosis." (PMID 18439274, 2008). "To eliminate the interference of nonspecific responses induced by viral infections, we infected monocytes with influenza A virus H3N2 (H3N2) and analyzed the impact of H3N2 infection of monocytes on the proliferation of CD4+ T-cell subsets." (PMID 39656009, 2025). "Following acute virus infection, the total CD8+ and CD4+ T cell response remained unaffected by the absence of NFATc1 or NFATc2 in the spleen or lymph nodes at 7 dpi." (PMID 38346075, 2024). "In a first step we compared transplant modalities, HSCT outcomes and IR data of CD3, CD4, CD8, TCR αβ, TCR γδ, Vδ1, Vδ2 and non-Vδ1/non-Vδ2 T cells between patients with and without viral infections." (PMID 39136029, 2024). "iKIR expression on CD4+ and CD8+ T cells is low and not significantly increased by chronic virus infection." (PMID 37071474, 2023). "CD3+CD4+CD8+ DP T cells are a distinct, minor population of cells that are particularly detectable in viral infections and have both cytotoxic and immunosuppressive properties." (PMID 37034572, 2023). "In conclusion, fractional doses of the 17D-213 yellow fever vaccine are safe, effective, and immunologically non-inferior to standard doses in HIV-infected individuals on antiretroviral therapy with CD4+ T-cell counts of at least 200 cells per mL." (PMID 37127045, 2023).
viral infection (continued). "During acute viral infection, absence of SPP in the eye did not affect CD4 expression but did affect CD8α and IFNγ expression in the eye." (PMID 36215312, 2022). "While CD8+ T cells are essential for viral clearance during acute viral infections in response to most respiratory viruses, we did not appreciate an increase in CD8+ T cell frequency or CD4:CD8 ratio." (PMID 35746678, 2022). "CD4+ T-cell immune reconstitution is widely used and is a strong predictor of event-free survival (EFS), overall survival (OS), viral diseases, and reactivation or non-relapse mortality (NRM), depending on stem cell transplant indications." (PMID 35242727, 2021). "In the setting of acute viral infections, the induction of an efficient CD8+ T cell response does not always require CD4+ T cell help." (PMID 33430234, 2021). "Another chronic viral infection, HCV, did not lead to reduction in the proportion of CD73+ memory CD4+ T cells compared to healthy controls." (PMID 33477692, 2021). "Thus, antigen-specific CD4 T cells provide help to promote expansion and acquisition of effector function for both CD8 T cells and B cells; they may also manifest MHC class II-restricted cell-mediated cytotoxicity, which is important for clearing persistent viral infections." (PMID 32462053, 2020). "Analysis of spleens from LCMV infected mice showed that thefrequencies of apoptotic cells increased during viral infection only among CD8+T cells, but not CD4+ T cells." (PMID 32944180, 2020). "Deficiency in β/γ-catenin did not detectably affect differentiation of CD4+T follicular helper cells or that of effector and memory CD8+ cytotoxic cells in response to acute viral infection." (PMID 32820720, 2020). "During virus infection, CD8+ T cells urgently require CD4+ T cells because CD8+ T cell functions are seriously damaged and are gradually reduced without the assistance of CD4+ T cells." (PMID 31390978, 2019). "The CD4/CD8 T cell ratio, which can be decreased after viral infection, was not affected in the skin or the blood of DSS cases compared to healthy controls." (PMID 29079750, 2017). "T-bet expression was not defective in CD4 and CD8 T cells from CD2-specific Egr2/3−/− mice in response to virus infection; indeed, T-bet+ CD4 T cells were higher in CD2-specific Egr2/3−/− mice." (PMID 28455436, 2017). "Cells staining for CD4 and CD8 were also present at low levels in the lamina propria prior to viral infection (CD4 staining not shown)." (PMID 29114252, 2017). "Among viral infections, CMV is considered a potent immune activator, and even in patients without immunodeficiency it can activate both CD4+ and CD8+ lymphocytes." (PMID 26355305, 2015). "Upon activation, previously latent HIV-1 infected memory CD4+ T cells and other cell types, which are not targeted by HAART therapy, can reseed viral infection." (PMID 25946221, 2015). "Thus, the different degree of actin polymerization in naïve and memory CD4+ T cells may induce distinct cellular receptor recruitment in both T cell subtypes, which in turn, may affect the efficiency of HIV-antigen internalization, in both cell-free and cell-to-cell virus infection." (PMID 24244453, 2013). "For neonatally rats, it was assumed that the lack of weight gain was due to the virus infection itself but in experimental LCMV-infection of mice, weight gain correlated with CD4+ T-cell activation rather than with TNF expression." (PMID 22848506, 2012). "In our study, 2-LTR CJ were not detectable from uncultured magnetic column-isolated CD4+ T cells; however, ex vivo activation of these sorted cells resulted in detectable 2 LTR CJ, consistent with the concept of a productive viral infection." (PMID 22314004, 2012). "In the absence of Themis, CD4+ T cells readily differentiate into TFH cells, while progenitor cells are depleted, leading to enhanced GC responses and antibody production, as well as better protection against persistent viral infection." (PMID 40777021, 2025).
viral infection (continued). "Since CD62L downregulation occurred in HIV infected p24+ but not p24- cells as evidenced in an increase of CD4-/CD62L- cells in p24+ but not p24- populations nor in the uninfected samples, thus CD62L shedding is primarily induced by the viral infection." (PMID 38572241, 2024). "One potential limitation of this study is that the functionality of CD4+ T cells was not determined directly, and these cells may be altered in PWH due to the viral infection." (PMID 38812512, 2024). "CD4 T cells with a higher TCF-1 expression have been shown to have self-renewing capacity, while CD4 T cells with a lower TCF-1 expression do not, at least in the context of a viral infection." (PMID 36901757, 2023). "However, no significant alteration was observed in CD4+ and CD8+ T cell numbers by either of the single-virus infections." (PMID 35107382, 2022). "This may be because earlier findings highlighting the CD4/CD8 T cell ratio, i.e., if decreased, supportive of suspected viral infection and, if increased, supportive of suspected MS, were not confirmed by more recent studies." (PMID 35054246, 2021). "In the present study, we demonstrate that RO and IVag ZIKV infection both induce robust antigen-specific Th1, TFH, plasma cell, GC B cell, IgM, and IgG responses, and that CD4+ T cells contribute to the generation of Ab responses, but not CD8+ T cell responses, and to the control of viral infection." (PMID 30677097, 2019). "Although the 4 vectors transduced the T cells with different efficiency, the percentages of CD4+ and CD8+ cells did not significantly vary among different virus-infected groups, suggestion that virus infection did not alter the inherent growth pattern of T cell subgroups." (PMID 31014302, 2019). "Several recent studies have uncovered a profound change in the balance of adipose tissue CD8+ and CD4+ T cells in PLWH, and similar studies in SIV-infected macaques indicate that the relative enrichment of CD8+ T cells stems from viral infection rather than from ART treatment or CD4+ cell depletion." (PMID 30941121, 2019). "We found that adenovirus could transduce more CD4+ cell than CD8+ cells, and viral infection did not change the ratio of CD4+/CD8+." (PMID 31014302, 2019). "The high frequency of CD3 cells on day 5 pi could not be accounted for by adding the total number of CD4+ and CD8+ cells, suggesting that other CD3 co-expressing cell populations may be recruited to the nasal turbinates following viral infection." (PMID 29114252, 2017). "Thus, the inability of CD4+ and CD8+ T cells to affect LACV-induced neurological disease in weanling mice is not due to an inability of these cells to respond to virus infection." (PMID 28340587, 2017). "Furthermore, the percent of CD4+ and/or CD8+ T cells lacking CD28 expression also correlated with miRNAs regulating clusters of genes known to be involved in viral infection." (PMID 27853459, 2016). "In addition, during certain viral infections T1IFN can provide a potent “signal 3,” aiding in the activation of CD8+ T cells, even in the absence of CD4+ T cell help." (PMID 27580079, 2016). "Although we cannot exclude that CD4+ and CD8+ T cells with other specificities may help reduce viral infection, the lack of serum cross-reactive antibodies further corroborates the most likely protective effect of M158-specific CD8+ T cells." (PMID 27036323, 2016). "Furthermore, transfer experiments revealed that animals receiving CD4+ T cells combined with anti-NS1 antiserum, both obtained from vaccinated mice, survived virus infection with survival rates not significantly different from pcTPANS1-immunized animals." (PMID 26650916, 2015). "Furthermore, at least in certain virus infections, type I IFN is able to promote anti-viral CD8+ T-cell responses without dependence on CD4+ T cell help." (PMID 24466045, 2014).
viral infection (continued). "However, we observed a persistent infiltration of CD4+ and CD8+ T cells in the liver after viral infection, suggesting that reduced viral clearance is not primarily the result of defective CD8+ T-cell migration." (PMID 23141740, 2013). "Unlike cell-free virus infection, our short-term coculture model between HIV-infected and non-stimulated primary CD4+ T cells maximise the cell-to-cell endocytic antigen transfer, which might determine differences in the infection outcome." (PMID 24244453, 2013). "There is growing evidence that both (CD4+) T helper cells and (CD8+) cytotoxic T lymphocytes not only play an important role in controlling viral infection, but also may reduce the severity of disease and decrease mortality." (PMID 24300513, 2013). "The result demonstrated that irrespective of their CD4 count both MUC5B and MUC7 mucins from HIV patients, unlike those HIV negative patients, failed to inhibit HIV-1 activity and a 100% viral infection of the CEM SS cells was measured by the p24 antigen assay after a 30 min incubation period." (PMID 20946627, 2010). "The concentrations of AMD3100 necessary to achieve 50% inhibition of HIV-1-LAI passage across the BeWo cells monolayer were 1.6 and 3 times, for CD4 negative and positive BeWo cells, respectively, higher than the IC50 required to block cell-free virus infection of PBMC." (PMID 18377645, 2008). "To examine whether CD4 T cells become exhausted due to the lack of TCF-1 in alloimmunity, as is shown during T cell responses to viral infection, we examined the Ki-67 expression and TOX expression, in CD4 T cells from WT C57Bl/6 and TCF-1 cKO mice before and after stimulation." (PMID 36901757, 2023). "Interestingly, unlike in other hepatotropic viral infections, HBV/HDV co-infection showed the highest percentage of cytotoxic CD4+ T cells in a comparative study of HBV, HCV, and HBV/HDV mono/co-infected individuals; however, CD4+ T cells were studied on an antigen-nonspecific level." (PMID 35215790, 2022). "On the other hand, the significant increase in the ratios of total CD3+ and CD4+ T cells and the ratios of activated (CD25+) CD8+ T cells and the level of the Th1 cytokine and inhibitor IL-10 between the negative control and positive control mice that had an only viral infection." (PMID 34349145, 2021). "However, B cells can be the dominant antigen-presenting cells that activate naive CD4+ T cells in certain circumstances, and B cells activated by TLR9 and TLR7 ligands in the context of viral infection are sufficient to induce Tfh development in the absence of DCs." (PMID 34197340, 2021). "Interestingly, studies show that activated B cells negatively regulate CD4+ T cell proliferation and APC function, indirectly attenuating the generation of effective CTL, however this has not been investigated in human viral infections." (PMID 24739950, 2014). "Therefore, although the TLR-ligand (CpG, in the present study) was necessary to mimic viral infection in order to induce CTL responses in the immunization with liposome-coupled peptides, CD4+ T cells were not required for the induction and maintenance of CD8+ memory T cells." (PMID 21264321, 2010). "Additionally, Ang II did not activate the anti-inflammatory CD4+ CD25+ regulatory T-cells, indicating the role of Ang II in triggering an inflammatory response and that compensatory systems physiologically stimulated during inflammation and following virus infection are not affected by Ang II." (PMID 35955801, 2022). "However, no cytotoxic CD4+ T cell response could be demonstrated during SARS-CoV-2 infection, which may not be too surprising since these cells were found mainly in chronic and not in acute self-limiting viral infections." (PMID 32948688, 2020).
viral infection (continued). "Interestingly, the CD8:CD4 ratio was similarly elevated (1.59) in non-infected animals with chronic enterocolitis, suggesting chronic illness or inflammation may affect adipose CD8+ and CD4+ T cell trafficking independently of viral infection." (PMID 30559739, 2018).